RARA (retinoic acid receptor alpha)
Diseases named in the same sentence as RARA in open-access papers (continued):
Sharing a sentence is not in itself a finding about the gene and the disease.
acute promyelocytic leukemia (continued). "Around 98% of cases of acute promyelocytic leukemia (APL) are characterized by the juxtaposition of the promyelocytic leukemia gene (PML) and the retinoic acid receptor α (RARα)." (PMID 31555592, 2019). "Guarnerio studied two types of leukemia, acute promyelocytic leukemia (APL) with translocation between PML and RARα, and AML with translocation between MLL and AF9." (PMID 31306100, 2019). "Acute promyelocytic leukemia (APL) is a kind of acute myeloid leukemia, which was characterized by the presence of PML/RARα fusion gene." (PMID 30200136, 2018). "Moreover, ATRA works only PML-RARAα containing APL patients, and not in RA-resistant promyelocytic leukemia zinc finger (PLZF)-RARα patients." (PMID 30237857, 2018). "Retinoic acid, in the form of ATRA, is used with great success in the clinical setting for a subset of acute promyelocytic leukemia patients who have chromosomal translocations involving the retinoic acid receptor-α gene, RARα, but the use of retinoids in solid tumors has not been promising to date." (PMID 18560594, 2008). "The 5th edition of the World Health Organization (WHO) Classification of Hematolymphoid Tumors recognizes acute promyelocytic leukemia (APL) as a subtype of acute myeloid leukemia (AML) defined by the presence of a genetic abnormality, namely the PML::RARA gene fusion." (PMID 40095699, 2025). "Acute promyelocytic leukemia (APL) comprises 5–10% of AML cases and is characterized by the presence of a fusion between the transcription factor promyelocytic leukemia (PML) and the retinoic acid receptor α (RARA) genes." (PMID 40849353, 2025). "Acute promyelocytic leukemia (APL) is a type of AML characterized by an accumulation of immature granulocytes, promyelocytes, that harbor genetic translocations in the retinoic acid receptor alpha gene (RARα) that generates the PML/RARα gene, PRα." (PMID 36694243, 2023). "However, very few patients have typical morphological and immunophenotypic characteristics of APL (e.g., promyelocytes containing coarse azurophile granules and Auer bodies) but are negative for promyelocytic leukemia-retinoic acid receptor alpha (PML-RARA) fusion." (PMID 36465368, 2022). "Similarly, the promyelocytic leukemia-retinoic acid receptor α (PML/RARα) has two primary NLS, which include one from the PML (159RNKKKK164), and the other from the RARα (486RKVIK490), the NLS of the RARα portion in NLS-RARα is more favorable for the nuclear localization of NLS-RARα." (PMID 34022911, 2021). "In acute promyelocytic leukemia (APL), FNDC3B may promote pathogenesis by fusing to retinoic acid receptor α (RARA)." (PMID 32272554, 2020). "Furthermore, atRA is highly effective as a therapeutic agent in acute promyelocytic leukemia (APL), a subtype of AML characterized by fusion proteins involving RARα." (PMID 31822659, 2019). "Acute promyelocytic leukemia (APL) is a distinct subtype of AML that is characterized by a specific chromosome translocation, which results in the fusion of the promyelocytic leukemia (PML) gene and the retinoic acid receptor α gene (RARα)." (PMID 25797266, 2015). "Although the blast cells in AML showed typical morphological and immunophenotypical features of acute promyelocytic leukemia (APL), it did not harbor RARα gene fusion and thus initially diagnosed as APL-like leukemia (APLL)." (PMID 36874114, 2023). "Although a direct role for RARA in PAX5-altered B-ALL has not been established, previous work has identified PAX5 as a target gene of the PLZF-RARA fusion protein in acute promyelocytic leukemia." (PMID 38116118, 2023). "PML‐retinoic acid receptor α (RARA) fusion proteins have dominant‐negative effects on PML body assembly and cause transcriptional repression of differentiation genes in acute promyelocytic leukemia (APL)." (PMID 36117111, 2022).
acute promyelocytic leukemia (continued). "As is known to all, acute promyelocytic leukemia (APL) is a particular subtype in AML, characterized by a balanced reciprocal translocation between chromosomes 15 and 17, which leads to the fusion between promyelocytic leukemia (PML) gene and retinoic acid receptor α (RARα)." (PMID 32400873, 2020). "Acute promyelocytic leukemia (APL) is a subtype of AML characterized by a reciprocal and balanced translocation involving retinoic acid receptor α (RARa) on chromosome 17 and promyelocytic leukemia (PML) on chromosome 15 which generates the oncogenic PML-RARα fusion protein." (PMID 31905996, 2019). "A case of acute promyelocytic leukemia (APL) with RUNX1T1 insertion to 7q is described and compared to reported cases of APL with negative retinoic acid receptor alpha (RARA) abnormality." (PMID 26351594, 2015). "They resemble classical acute promyelocytic leukemia (APL) patients in clinical features, morphology, and immunophenotype but do not carry the promyelocytic leukemia (PML)-RARA fusion gene." (PMID 36185228, 2022).
leukemia (202 papers, 2007 to 2026). A malignant (clonal) hematologic disorder, involving hematopoietic stem cells and characterized by the presence of primitive or atypical myeloid or lymphoid cells in the bone marrow and the blood. "In leukemia cells, retinoic acid activated RARα/Sp1, whereas RARβ and RARγ were associated with both AP1 and Sp1 binding sites in the FRβ gene promoter, and the ets protein was also associated with Sp1." (PMID 39858066, 2025). "This leukemia has unique characteristics, such as its association with chromosomal translocations involving the retinoid acid receptor α (RARA) gene on chromosome 17." (PMID 38023223, 2023). "Mutations in RARA gene, mostly resulting in fusion genes, are associated with abnormality of blood forming tissues, leukemias and deregulate genes involved in DNA repair." (PMID 31266445, 2019). "This leukemia mainly causes due to translocation between retinoic acid receptor alpha (RARα) gene and acid promyelocytic leukemia (PML) gene." (PMID 29911120, 2018). "Resistance to physiological RA growth-inhibitory action was traced for the first time to RARA transcriptional inactivity due to leukemia-associated dominant negative RARA mutations, which determines genome-wide epigenetic deregulation of RARA-target genes." (PMID 27894085, 2016). "However, some relapsed patients develop resistance to ATO due to mutations in the promyelocytic leukemia (PML) part of the PML::RARα fusion gene." (PMID 40330660, 2025). "Linkage of PML to RARA generates a PML-RARA oncoprotein that acts as a transcription factor that deregulates transcriptional programs blocking the differentiation of hematopoietic progenitor cells and thus causing leukemia." (PMID 36880596, 2023). "Interestingly, the effect of ATRA‐induced differentiation is insufficient for APL eradication, whereas only PML/RARA loss fully extinguish leukaemia‐initiating activity." (PMID 35001521, 2022). "Their fusion gene was respectively generated between exon 15 or 13 of FIP1L1 and exon 3 of RARA, while the reason for two different phenotypes of leukemia caused by FIP1L1–RARA is still unknown." (PMID 34249738, 2021). "The PML (promyelocytic leukemia) protein, a tumor suppressor protein that is frequently implicated in leukemia, is best known for its translocation with the retinoic acid receptor alpha (RARa) resulting in the PML-RARa protein, and for the organization of PML nuclear bodies." (PMID 33670160, 2021). "In addition, our results were unable to observe significant association of the methylation of CDKN1C and RARA genes with leukemia." (PMID 24810788, 2014). "Reasons for different phenotypes of leukemia caused by FIP1L1::RARA remain unknown." (PMID 36776354, 2022). "Another example of this chimeric protein formation by chromosomal translocation is PLZF-RARα (fusion protein of the zinc finger of the promyelocytic leukemia protein with RARα)." (PMID 40284012, 2025). "In acute promyelocytic leukaemia (APL), which has a chromosome translocation resulting in the fusion gene of the retinoic acid receptor alpha (RARα), retinoic acid produces differentiation of leukaemia cells and achieves excellent clinical results." (PMID 40673272, 2025). "The ELN also stipulates suitable molecular biomarkers, highlighting leukemia initiating variants (e.g., NPM1, CBFB::MYH11, RUNX1::RUNX1T1, PML::RARA) essential in disease monitoring." (PMID 38891959, 2024). "Genomes with chromosomal rearrangements can also produce fusion circular RNAs (f-circRNAs) by backsplicing of chimeric transcripts, as first shown in leukemias with PML::RARα and KMT2A::MLLT3 translocations and later in solid cancers." (PMID 36585787, 2023). "Biologically, mice transgenic for the fusion gene PML::RARA manifested a pre-leukaemic state of deranged myeloid maturation, with an APL-like leukaemia only developing if collaborating mutations such as internal tandem duplication of FLT3 were present." (PMID 36765318, 2023).
leukemia (continued). "Recently, ATO‐resistant APL patients having RA‐resistant promyelocytic leukaemia zinc finger (PLZF) RARα have been reported worldwide." (PMID 35946055, 2022). "Altogether, these results further demonstrated that FTO and its downstream targets (e.g., MYC, RARA) are the major effectors of SsD in FTO overexpressed leukemia cells." (PMID 33897884, 2021). "In patients with APL, a reciprocal chromosomal translocation of the RARα gene on chromosome 17 and the promyelocytic leukaemia (PML) gene on chromosome 15 results in a PML-RARα fusion protein." (PMID 34785649, 2021). "The oncoprotein PML/RARα drives to deregulation of transcription, differentiation arrest, and enhanced self-renewal of leukaemia-initiating blast cells." (PMID 33907248, 2021). "As the in vivo effects of isolated EGCG in AML have not yet been evaluated, the aim of this study was to evaluate the molecular mechanisms involved in anti-leukaemia activity of EGCG using the acute promyelocytic leukaemia (APL) model (PML/RARα)." (PMID 33907248, 2021). "Since the discovery of PML-RARA, more than a dozen diverse translocations involving RARA have been found in rare leukemia patients, often with typical morphological features of APL." (PMID 32295268, 2020). "They analyzed the prognostic impact of APL with alternative RARA or RARG fusions, showing that the 3-year overall survival (OS) and leukemia-free survival (LFS) of APL with alternative RARA or RARG were worse than that of PML-RARA cohort." (PMID 31207999, 2019). "APL is a distinct subtype of acute myeloid leukemia that expresses the promyelocytic leukemia-retinoic acid receptor alpha (PML-RAR-alpha) oncoprotein and is characterized by severe bleeding resulting from increased plasmin production." (PMID 30621740, 2019). "This translocation leads to the fusion of the retinoic acid receptor-α (RARα) gene and promyelocytic leukemia (PML) gene, resulting in the formation of the PML/RAR-α fusion protein, which is involved in leukemogenesis." (PMID 30225259, 2018). "Recent studies have also shown that in leukaemia with PML/RARα translocations, a type of special fusion-circRNA can be generated during the generation of fusion-gene." (PMID 28535767, 2017). "RARα plays a critical and central role in mediating the RA-induced terminal differentiation of leukemia cells." (PMID 27074819, 2016). "PLZF/RARA acts as an oncogenic transcriptional regulator in leukemia and as an important regulator in cell cycle progression, which is induced by diverse checkpoint regulators." (PMID 26427597, 2015). "For instance, overexpression of retinoic acid receptor alpha (RARα) due to its fusion to PML (RARα/PML) and estrogen receptor alpha (ERα) expression cause onset of leukemia and breast cancer progression, respectively." (PMID 26244663, 2015). "In the majority of PML-RARα+ AML patients, retinoic acid receptor alpha (RARα) is fused to the promyelocytic leukemia (PML) open reading frame on chromosome 15." (PMID 26179601, 2015). "Topoisomerase II administration is associated with known balanced translocations including the MLL (mixed-lineage leukemia) gene at 11q23 or PML/RARA (promyelocytic leukemia/retinoic acid receptor, alpha) gene." (PMID 26798525, 2015). "Previously, we reported that oridonin increased RARα protein levels and antagonized ATRA-induced RARα loss in leukemia cell lines." (PMID 25886043, 2015). "Mice inoculated with PML/RARα- or DEK/NUP214-positive leukemic cells developed leukemia with a latency of approximately 4 weeks and a penetrance of 100%." (PMID 25568664, 2014). "To identify the cell population that maintains the PML/RARα- or RUNX1/RUNX1T1-positive leukemias, we transferred 2×104 cells from leukemic mice, with a tumor load of at least 80%, into sublethally irradiated secondary recipient mice." (PMID 25568664, 2014).
leukemia (continued). "In contrast to our model, these findings were obtained using an already established leukemia based on the expression of PML/RARα driven by promoters mainly active in committed progenitors, but also in the LT-HSC compartment, even at a lower level." (PMID 25568664, 2014). "To compare the cell population maintaining PML/RARα-positive leukemia with the L-IC population, we sorted the principal subpopulations for transplantation into sublethally irradiated recipients." (PMID 25568664, 2014). "DEK/NUP214 and PML/RARα exert their leukemogenic potential on a very small subpopulation of HSC explaining the low penetrance of leukemia from PML/RARα- and DEK/NUP214-transduced HSPCs." (PMID 25568664, 2014). "The established PML/RARα-positive leukemia was composed of 73% linlo/- cells, 65% of which were already committed Sca1−/c-Kit− cells, 13.5% were Sca1−/c-Kit+ and 1.5% presented the stem-cell phenotype of Sca1+/c-Kit+." (PMID 25568664, 2014). "This is noteworthy because it clearly represented the population that was transformed by PML/RARα to initiate leukemia." (PMID 25568664, 2014). "Together, these data suggest that OA exerts a cytotoxic effect that inhibits proliferation and induces apoptosis in NB4 cells by targeting PML/RARα, making it a potent therapeutic agent against leukemia." (PMID 24137431, 2013). "Targeting the fusion protein/co-repressor contact was reported to restore a differentiation response in leukemia cells expressing PML/RARα or AML1/ETO." (PMID 23152790, 2012). "We previously demonstrated that promyelocytic leukemia/retinoic acid receptor alpha (PML/RARa) hybrid protein inhibits Nrf2 function, impedes its transfer to the nucleus, and enhances its degradation in the cytoplasm, but mRNA levels are similar to those found in other AML subtypes." (PMID 40422216, 2025). "FTO downregulates m6A levels, modulates the expression of Ankyrin Repeat and SOCS Box Containing 2 (ASB2) and Retinoic Acid Receptor Alpha (RARA), enhances gene-mediated cell transformation and leukemia onset, and inhibits acute myeloid leukemia (AML) cell differentiation." (PMID 38711100, 2024). "Despite demonstrating the ability of leukemia cells carrying the PLZF::RARα fusion to fully differentiate with both ex vivo and in vivo ATRA treatment, the clinical reality is that APL with this rare fusion is commonly considered ATRA-insensitive and is linked to an unfavorable prognosis." (PMID 38835381, 2024). "Moreover, ATO mediated TBLR1-RARα protein degradation via proteasome pathway, which accounts for the transcriptional activation of RARα target gene and is further involved in cell differentiation of TBLR1-RARα positive leukemia cells." (PMID 35517404, 2022). "Given the high relapse rate, patients with STAT5B/RARA-positive leukemia might benefit from hematopoietic stem cell transplantation in the first remission." (PMID 35494081, 2022). "Previous studies have shown that PML/RARα is necessary but not sufficient to cause leukemia, and cooperating events are required for the development of APL7,8." (PMID 33298855, 2020). "ATRA is a RARA agonist, which revealed clinical efficacy in leukemia treatment." (PMID 30123134, 2018). "The APL is 1 kind of AML characterized by the balanced reciprocal translocation between the promyelocytic leukemia gene on chromosome 15 and the retinoic acid receptor α (RARα) gene on chromosome 17, and accounts for 10% to 15% of newly diagnosed AML each year." (PMID 30200136, 2018). "The precise leukemogenic mechanism of the PML/RARA oncoprotein has not been fully elucidated, and its presence in transgenic mice is not per se sufficient to cause leukemia, but leads to a myeloproliferative syndrome." (PMID 27626703, 2016). "Interestingly, Let-7a is reported to impart chemoresistance in AML cells bearing NPM mutations while increased Let-7c expression can promote granulocyte differentiation of PML/RARα leukemia cells." (PMID 27007052, 2016).